INS (insulin)
Diseases named in the same sentence as INS in open-access papers (continued):
Sharing a sentence is not in itself a finding about the gene and the disease.
diabetes (continued). "Insulin introduced a paradigm shift in diabetes management from extreme dietary carbohydrate restriction to effective lowering of blood glucose with insulin treatment." (PMID 36845885, 2023). "Insulin was the first peptide hormone discovered in 1922 during the examination of pancreatic extracts in diabetes research." (PMID 37372966, 2023). "The severity and course of diabetes are variable and glucose homeostasis ranges from normoglycemia to insulin-treated diabetes with ketoacidosis at onset." (PMID 36672242, 2023). "Those with lower eGDR were older with a longer diabetes duration, higher insulin requirements, and an adverse vascular profile (p < 0.05)." (PMID 36495341, 2023). "To investigate the possible mechanisms behind the potential benefits of folates in diabetics, we studied the correlation between folate intake and plasma homocysteine blood glucose, insulin levels, HOMA-IR and HOMA-β function index, and inflammatory indices." (PMID 38068801, 2023). "The MWF-D group exhibited the classical features of diabetes, i.e., higher water intake, higher urine volume, and increased glycosuria, whose increase was prevented by insulin treatment in the MWF-D-ins group." (PMID 38069331, 2023). "The avoidance of hypoglycemia is crucial in managing diabetes and can be achieved through self-care behaviors such as blood glucose testing and insulin dose adjustment." (PMID 37838688, 2023). "– Gastrointestinal tract inoculation of chitosan-based insulin genetic compounds to rats that have diabetes.– Outcome: rapid reduction in the amount of FBS of the rats inoculated with chitosan-DNA particles." (PMID 37621841, 2023). "Various animal models have been studied that have demonstrated the role of aldose reductase in cataract formation after inducing diabetes by either pancreatomy or chemical ablation of the beta cells responsible of insulin production in the pancreas." (PMID 37395905, 2023). "Diabetes mellitus is a long-term metabolic disorder characterized by hyperglycemia due to impaired of insulin secretion, insulin function or both." (PMID 36788517, 2023). "The patient was switched to a self-administered diet for diabetes and given subcutaneous insulin injections while adjusting the insulin dose based on blood glucose levels." (PMID 37286981, 2023). "Another animal study revealed that ozone exposure in rats promotes the development of diabetes by activating the JNK pathway to impair insulin signaling in muscles." (PMID 38250975, 2023). "There is significant improvement in blood glucose, plasma insulin, glucose tolerance, β cell proliferation, and β cell mass, resulting in the reversal of diabetes in OPG-treated versus control saline- or immunoglobulin G (IgG)–treated diabetic NOD mice." (PMID 37910614, 2023). "The most advanced diabetes technologies have the potential to do so, with automated insulin adjustments and dosing calculated through an algorithm linking a CGM to an insulin pump." (PMID 38096018, 2023). "Type 2 diabetes mellitus (T2DM) is a multi-factorial endocrine disorder characterized by alteration in insulin secretion, the presence of insulin resistance (IR), and a compensatory increase in hepatic gluconeogenesis." (PMID 37706122, 2023). "The first aim was to examine young people’s and their caregivers’ experiences and preferences regarding insulin pumps, sensor technologies, and diabetes communication technologies in an exploratory manner." (PMID 36696176, 2023). "In the cross-sectional study by Chen and his colleagues, 83.5% of all insulin-treated patients with diabetes had current HbA1c levels <7%, comparable to our findings." (PMID 37264625, 2023). "More than 20% of patients in this study were on concomitant treatment with metformin and insulin, indicating the likely selection of the more severe cases of diabetes." (PMID 36380441, 2023).
diabetes (continued). "In order to avoid the influence of hypoglycemic treatment and the diabetes duration on insulin function and insulin resistance as much as possible, the subjects of this study were newly diagnosed T2DM patients." (PMID 37893213, 2023). "Currently, oral and injectable antidiabetic drugs, insulin therapy, and lifestyle management are the primary therapeutic modalities used to treat diabetes." (PMID 37175825, 2023). "Her admission to the ICU was due to diabetic ketoacidosis resulting from poor compliance with insulin therapy." (PMID 37980489, 2023). "Diabetes mellitus (DM) is characterised by persistent hyperglycaemia which results from defects in the secretion or action of insulin." (PMID 37176684, 2023). "Some scholars emphasized that diabetes patients are commonly accompanied by lipid metabolism disorder and hyperlipidemia due to the dysfunction of insulin biological regulation." (PMID 37223032, 2023). "Insufficient insulin synthesis or inefficient insulin usage are the hallmarks of diabetes mellitus which is a metabolic disorder." (PMID 37581127, 2023). "The model includes modules for insulin bolus injections and meal intake as additional inputs to capture all aspects of daily life and diabetes management, allowing simulation of realistic scenarios." (PMID 36791144, 2023). "In comparison to insulin treatment of diabetics, our experiment returned a statistically stable decrease in lens opacity for rodents treated with AuNPsR (p < 0.001)." (PMID 37623898, 2023). "Developing a similar model of care locally, particularly targeting those receiving insulin treatment, is likely to improve the way diabetes care is being delivered." (PMID 37152098, 2023). "The coexistence of T1DM and another autoimmune disease in the same patient has a major impact on the patient’s quality of life, affecting glucose metabolism, preventing effective insulin therapy, and influencing diabetes control." (PMID 36983604, 2023). "These clearly proved the anti-inflammatory potential of C. papaya to regulate the insulin sensitivity in diabetes mellitus." (PMID 36826001, 2023). "Specifically, within a month of receiving ECHO Diabetes support, his HbA1c decreased to 10.8%, and his insulin dose was further reduced." (PMID 37535407, 2023). "Half of the diabetes patients were equipped with an insulin pump and/or had an FSL device for continuous glucose monitoring." (PMID 37048770, 2023). "One review found a rate of psychiatric disorder in type 2 diabetes of 7% in studies with a low risk of bias and the correlates were female sex, lower age, few years of education, complications of diabetes, living alone, use of insulin." (PMID 37253033, 2023). "In adoptive transfer, the insulin-specific CD8+ T cells are highly pathogenic; they require pre-activation in order to cause diabetes, and normally diabetes is adoptively transferred in 7–14 days." (PMID 37731505, 2023). "Although insulin administration remains crucial, blood glucose control through self-monitoring plays a pivotal role in preventing diabetes-related complications." (PMID 38666044, 2023). "Diabetes is a complex metabolic disorder characterized by elevated blood glucose levels due to insulin resistance, insufficient insulin production or both." (PMID 37434784, 2023). "Vitamin D can act directly on pancreatic β-cells, affecting insulin secretion, improve insulin sensitivity through vitamin D receptors in insulin-sensitive organs, and reduce oxidative stress in patients with diabetes." (PMID 37795357, 2023). "Diabetes, a medical condition characterized by elevated blood glucose levels resulting from impaired insulin action or secretion, has become a significant global epidemic." (PMID 37868469, 2023). "Insulin exposure varies over 3 days of insulin infusion set (IIS) wear making day-to-day insulin dosing challenging for people with diabetes (PWD)." (PMID 36342853, 2023).
diabetes (continued). "The onset of diabetes promotes the impairment of insulin secretion and high systemic glucose levels." (PMID 37108202, 2023). "Patients with diabetes commonly exhibit impaired brain insulin signaling which, in turn, facilitates cognitive deficit development (McNay and Recknagel, 2011; Kim and Feldman, 2015)." (PMID 36998706, 2023). "Insulin lispro 100 units/mL Jr KwikPen is the first prefilled, disposable, half‐unit insulin pen that delivers 0.5–30 units in increments of 0.5 units for the treatment of patients with diabetes." (PMID 37715339, 2023). "A meta-analysis indicated that probiotics significantly lowered hemoglobin A1c, fasting blood glucose, fasting insulin, triglycerides, and total cholesterol, and improved the symptoms of diabetes." (PMID 36839280, 2023). "And those, who I see, who for example has insulin-requiring diabetes, I have had a couple of patients who has that, it’s [diabetes] managed poorly”." (PMID 37372721, 2023). "This narrative review aimed to analyze the key recommendations by major global and national guidelines on the initiation of insulin therapy in patients with type 2 diabetes mellitus over the last 20 years." (PMID 36650625, 2023). "In most patients with type 1 diabetes mellitus, destruction of pancreatic beta cells that secrete insulin occurs through an autoimmune mechanism." (PMID 36979685, 2023). "Hypoglycemia is a common problem in patients with diabetes receiving insulin and/or insulin secretagogue therapy." (PMID 37964960, 2023). "Based on an in vitro experiment, Achari and Jain (2017) suggested that L-Cysteine supplementation can increase insulin sensitivity and can be used as adjuvant therapy for diabetes." (PMID 37784018, 2023). "The advantage of SLN in protecting proteins from enzymatic degradation in the gastrointestinal tract and enhanced uptake has been widely described in different studies regarding the oral delivery of insulin for the treatment of diabetes mellitus." (PMID 37376042, 2023). "Medication costs for diabetes patients constituted 43% of the total direct medical burden in the US in 2017 comprising $15 billion for insulin, $15.9 billion for other antidiabetic agents, and $71.2 billion in excess use of other prescription medications." (PMID 38124081, 2023). "One-third of the participants had T1DM, while 68.5% had T2DM, with median ages of 25 and 56 years, diabetes durations of 10 and 15 years, and durations of insulin use of 10 and 5 years, respectively." (PMID 37964960, 2023). "It is found that the melatonin is also responsible for glucose regulation and insulin release from pancreas which turns it into a possible goal for the management of the diabetes mellitus." (PMID 36782201, 2023). "In this experiment, we used the Boruta feature selection algorithm to select five features from the PIMA Indian diabetes dataset, namely, glucose, insulin level, body mass index, diabetes spectrum function and age." (PMID 37264332, 2023). "Patients with type 2 DM who need insulin therapy are considered to display one of the indicators of diabetes severity." (PMID 36707543, 2023). "For KEGG pathway analysis, the pyroptosis-related hub genes were enriched in maturity-onset diabetes of the young, insulin secretion, type 1 diabetes mellitus, and glutamatergic synapses." (PMID 36967805, 2023). "It showed that b-HbA1c was not a risk factor for the 3p-MACE in some subgroups (e.g., age ≥ 65 years, hypertension, duration of diabetes ≥ 12 months, insulin treatment, PCI, severe CHD, etc. p > 0.05)." (PMID 36935502, 2023). "frühzeitige Therapie scheinen ratsam (s. bitte Absatz Insulin-Resistenz und Diabetes bei Lipodystrophie Syndromen)." (PMID 37101022, 2023). "Traditional treatment methods, such as insulin therapy, oral hypoglycemic medications, and lifestyle changes, have played a fundamental role in managing diabetes." (PMID 38283440, 2023).
diabetes (continued). "Tight glycemic control during short‐term intensive insulin therapy (SIIT) is critical for inducing diabetes remission in patients with newly diagnosed type 2 diabetes (T2D)." (PMID 36650669, 2023). "The treatment of Type 1 Diabetes Mellitus (T1D) can be performed through continuous subcutaneous insulin infusion (CSII) or multiple daily injections (MDI)." (PMID 38093983, 2023). "This study showed for the first time, that using an ultrasensitive method for serum C-peptide, around 60% of long-term Brazilian T1D with childhood-onset (~ 17 yrs of diabetes duration) had residual insulin secretion." (PMID 36935525, 2023). "The most prevalent kind of diabetes is type 2, which often affects adults and develops when the body stops producing enough insulin or develops insulin resistance." (PMID 38022000, 2023). "In the present study at the TASH diabetes clinic, it was determined that diabetes patients generally had fair practices in insulin handling, storage, and administration techniques." (PMID 37143082, 2023). "Insulin use, diabetes’ complications and having T2DM at an early age all indicate the severity of diabetes." (PMID 36804018, 2023). "Phenotypes of diabetes tend to overlap, and many factors affect insulin secretion, importantly age and diabetes duration, as previous studies have already established." (PMID 37798422, 2023). "People with type 2 diabetes mellitus (T2DM) have abnormal secretion as well as the action of insulin." (PMID 37109046, 2023). "This analysis included a total of 13,133 ETNA-AF Europe participants, whereby 2885 patients had diabetes mellitus (22.0%), 605 of whom were on insulin therapy (21.0%)." (PMID 35976428, 2023). "The MD can exert a crucial impact in insulin-independent diabetes-related mechanisms due to the fact that it includes several anti-inflammatory or antioxidant ingredients, glucagon-like peptide agonist molecules, and alterations in intestinal microbiome." (PMID 38201865, 2023). "Accordingly, a lifestyle of routine muscle activation by bouts of exercise mitigates the development of diabetes through chronic adaptations but also via acute reduction of needed insulin after a meal." (PMID 37606407, 2023). "Overall, the combination of NAC with insulin appears promising in the treatment of canine type 1 diabetes mellitus." (PMID 37891946, 2023). "RVs such as murine stem cell virus (MSCV) have been used for expression of the human insulin gene in diabetic mice, showing decrease in blood glucose levels, increase in secreted insulin, and reversal of diabetes for up to 6 weeks." (PMID 36992407, 2023). "This study aimed to examine the difference in health-related quality of life (HRQOL) and diabetes-related healthcare events (HCEs) among adults with diabetes who were on metformin, sulfonylurea, insulin, or thiazolidinedione (TZD) monotherapy." (PMID 36833075, 2023). "The inflammasome can directly or indirectly affect conduction of the insulin signaling pathway, involvement the occurrence of IR and type 2 diabetes mellitus (T2DM)." (PMID 36993972, 2023). "Type-2 diabetes mellitus (T2DM) is a metabolic disorder that results from insulin depletion and/or failure of tissues to respond to insulin (insulin resistance) and metabolize glucose, which ultimately results in chronic hyperglycemia." (PMID 36831708, 2023). "TXNIP is associated with diabetes mellitus, specifically T2DM, and regulates diabetes-related cellular functions such as glucose homeostasis, insulin resistance, and pancreatic β cell function." (PMID 38137029, 2023). "The discovery of insulin in 1921 transformed the landscape of diabetes treatment and was followed by the discovery of several new therapies which improved glycemia and increased patient life span." (PMID 36845885, 2023). "A person diagnosed with diabetes needs to perform regular blood glucose control and monitoring, followed by adequate treatment, which means administering insulin using pens or pumps in the case of type 1 diabetes." (PMID 38201852, 2023).
diabetes (continued). "The potential application area of insulin sensing by ZnO nanorods will be real time monitoring of glucose for efficient management of diabetes." (PMID 37560710, 2023). "A total of 377 HFrEF patients who underwent cardiac MRI were included and divided according to diabetes status and the need for insulin treatment." (PMID 37542280, 2023). "Type 1 diabetes mellitus (T1DM) arises from the failure of pancreatic β-cells to produce adequate insulin, usually as a consequence of extensive pancreatic β-cell destruction." (PMID 36834709, 2023). "The diabetes pathology also promotes a deregulation of hormonal balance since insulin is an anabolic hormone." (PMID 37108202, 2023). "This study aimed to compare insulin status and dysglycemia (prediabetes/diabetes) of patients with chronic (stage III, grade B) or aggressive periodontitis (stage III, grade C) to that of a healthy population." (PMID 36651310, 2023). "The expression of trypsin-1, PAR1, PAR2, PAR3, and COX-2 increased in diabetes, and Mg2+/insulin treatment strongly decreased their expression." (PMID 37228689, 2023). "Multiple factors have been attributed to poorer diabetes control in this group, including the reduced use of technology such as insulin pump therapy and continuous glucose monitors, which are likely to improve diabetes control." (PMID 38090274, 2023). "Studies on p66Shc deletion in vitro in cell types other than pancreatic beta-cells have provided further data supporting the possible role of p66Shc in the pathogenesis of diabetes, mainly due to its insulin-signaling repressor activity." (PMID 38203279, 2023). "Risk factors of DKA include advanced diabetes, previous DKA, fasting, low-carbohydrate diet, dehydration, insulin insufficiency, reducing or omitting insulin and procedural or surgical stress." (PMID 36789141, 2023). "Diabetes mellitus is a cluster of metabolic disorders because of absolute or relative insufficient insulin secretion and less sensitivity of target cells to insulin, which is characterized by hyperglycemia." (PMID 37191432, 2023). "This is consistence with previous studies that diabetes is produced by a defect of insulin action, secretion, or even both factors." (PMID 37576166, 2023). "Oral INS delivery, as a more convenient treatment for diabetes, has the characteristics of simulating physiological INS secretion while overcoming these difficulties." (PMID 36986680, 2023). "They found that maternal age, pre-pregnancy BMI, FPG value, prior GDM, and family history of diabetes were predictors of insulin need." (PMID 37268897, 2023). "A 22-year-old North African female patient, first-year Master’s degree student with a history of diabetes mellitus on subcutaneous insulin treatment." (PMID 37980489, 2023). "In untreated STZ mice insulin levels continued to decrease with a concomitant increase in glucose levels, resulting in development of overt diabetes." (PMID 37626210, 2023). "Here we treat male STAM (STelic Animal Model) mice, which develop diabetes, NASH and HCC associated with dysbiosis upon low-dose streptozotocin and high-fat diet (HFD), with insulin or phlorizin." (PMID 37852976, 2023). "Patients who go on to experience diabetes-related complications because of their insulin restriction also express guilt over their prior actions." (PMID 38041170, 2023). "The feasibility of controlling hyperglycemia in diabetes through hepatic synthesis of insulin is attractive for researchers." (PMID 38019818, 2023). "Dietary and lifestyle modification are recommended approaches for managing diabetes, together with pharmacological interventions including oral hypoglycemic medications (e.g., glipizide, metformin, or acarbose) or ultimately insulin injections." (PMID 37032781, 2023). "Respondents with insulin treatment stated to a higher extent than others that they attended diabetes classes, but still had limited knowledge about diet." (PMID 37719056, 2023).